NOX1 (NADPH oxidase 1)
Diseases named in the same sentence as NOX1 in open-access papers (continued):
Sharing a sentence is not in itself a finding about the gene and the disease.
ulcerative colitis (2 papers, 2023). An inflammatory bowel disease involving the mucosal surface of the large intestine and rectum. "An immediate candidate from our work is NOX1, which has recently been shown to prevent inflammation, and its mutations were linked to ulcerative colitis." (PMID 36969163, 2023). "D360N, a well-characterized mutation rare among healthy populations, but rather common in Ashkenazi Jewish males with ulcerative colitis (UC), D360N, also engages in active interaction with FAD in both NOX1 and NOX2." (PMID 37134122, 2023).
vascular dementia (2 papers, 2017 to 2019). A degenerative vascular disorder affecting the brain. "Recently, we demonstrated that NOX1-mediated oxidative stress plays an important role in hippocampal neuronal degeneration and cognitive dysfunction in a vascular dementia animal model." (PMID 30736297, 2019).
abdominal aortic aneurysm (1 paper, 2025). Enlargement and ballooning of the vessel that supplies arterial blood to the abdomen, pelvis and legs. "•SMC-specific deletion of Nox1 reduces abdominal aortic aneurysm formation." (PMID 39721498, 2025).
acute pancreatitis (1 paper, 2018). An acute inflammatory process that leads to necrosis of the pancreatic parenchyma. "Consistent with previous reports, our study also showed that the expression of NOX1, p22phox, p47phox, and p67phox NOX subunits increased by Jak2 activation in caerulein-induced acute pancreatitis, whereas this increase was attenuated by dunnione treatment." (PMID 30584237, 2018).
allergic rhinitis (1 paper, 2019). Inflammation of the nasal mucous membranes caused by an IgE-mediated response to external allergens. "Noxa1 acts as a central component of NADPH oxidase (NOX), while Nox1 could affect reactive oxygen species (ROS) production, both of which might contribute to oxidative stress in allergic rhinitis." (PMID 30823938, 2019).
alveolitis (1 paper, 2013). "Interestingly the pattern of inflammation mirrored the localization pattern of Nox1, i.e. peri-vascular inflammation coinciding with Nox1 expression in endothelium, and the alveolitis coinciding with Nox1 expression in the alveolar epithelium." (PMID 23577160, 2013).
amyloid (1 paper, 2025). "Indeed, we observed in the hippocampi of dKI mice a significant increase in NOX1 and phosphorylated JNK/SAPK/total JNK at 6 months, while CDK5 was significantly increased by 12 months, suggesting that the UNC5C T835M-mediated apoptotic pathway was exacerbated by amyloid pathology in dKI mice." (PMID 40468412, 2025).
Aortic dissection (1 paper, 2018). Aortic dissection refers to a tear in the intimal layer of the aorta causing a separation between the intima and the medial layers of the aorta. "In order to understand its pathobiology, NOX1-deficient mice were treated with Ang-II and were shown to have reduction in aortic dissection and aneurysm." (PMID 30140678, 2018).
autism (1 paper, 2024). Persistent deficits in social interaction and communication and interaction as well as a markedly restricted repertoire of activity and interest as well as repetitive patterns of behavior. "Six genes were significantly differentially expressed between autism likelihood (social communication) groups: CYSLTR2, NOX1, C1QA, CXCL10, C8A, IL23R (all up-regulated, p < 0.05)." (PMID 39247132, 2024).
cardiac arrest (1 paper, 2024). Cessation of breathing and/or cardiac function. "Among a total of 62 cardiac arrest survivors (16 good, 46 poor), serum kallistatin were lower, and Nox-1 were higher in the poor neurological group at all time points after admission to the ICU (p = 0.013 at admission; p = 0.020 at 24 h; p = 0.011 at 72 h)." (PMID 38383562, 2024). "In the in-vitro study mimicking cardiac arrest, kallistatin knockdown cells exposed to OGD/Reoxy showed an increase in Nox-1 expression, H2O2 levels, and caspase-3 expression." (PMID 38383562, 2024).
cholangiocarcinoma (1 paper, 2025). A carcinoma that arises from the intrahepatic biliary tree (intrahepatic cholangiocarcinoma) or from the junction, or adjacent to the junction, of the right and left hepatic ducts (hilar cholangiocarcinoma). "Specifically, gut dysbiosis was shown to suppress the pro-death effects of the ferroptosis inducer FIN56 on HuCCT1 (a human intrahepatic cholangiocarcinoma cell line) by regulating the activin receptor-like kinase 5 (ALK5)/NADPH Oxidase 1 (NOX1) signaling axis." (PMID 41614790, 2025).
co-infection (1 paper, 2012). "Silencing of NOX1 reduced the co-infection induced production of ROS by 40% and rescued chlamydial infectivity to 33%." (PMID 23077614, 2012). "We silenced the expression of NOX1 and tested the effect on chlamydial persistence induced by co-infection." (PMID 23077614, 2012). "We therefore tested the involvement of NOX1 in co-infection induced deregulation of ROS production." (PMID 23077614, 2012).
Constipation (1 paper, 2022). Infrequent or difficult evacuation of feces. "NOX1 mRNA level in the colonic mucosa of patients with constipation was doubled compared to that in the controls (P < .05)." (PMID 35960091, 2022). "In IHC, NOX1 expression in the colon epithelial cells was increased in patients with chronic function constipation compared to control group (P < .05)." (PMID 35960091, 2022).
cutaneous squamous cell carcinoma (1 paper, 2018). "In addition, blockade of NOX-1 activation in response to UVB irradiation increases DNA nucleotide excision repair, decreasing genomic instability and formation of cutaneous squamous cell carcinomas." (PMID 29568383, 2018).
dementia (1 paper, 2023). Loss of intellectual abilities interfering with an individual's social and occupational functions. "New findings revealed that NOX1 inhibition may be applicable for neurodegenerative disorders causing dementia." (PMID 37134122, 2023).
dilated cardiomyopathy (1 paper, 2022). Cardiomyopathy which is characterized by dilation and contractile dysfunction of the left and right ventricles. "In dilated cardiomyopathy, Drp1 induced constitutive expression of NOX1 and NOX4 while promoted NLRP3 inflammasome activation through mitochondrial fission." (PMID 35711428, 2022).
enteritis (1 paper, 2025). Inflammation of the small intestine. "Among the members of the NOX family, NOX1, NOX2, and NOX4 are particularly relevant to enteritis." (PMID 40431496, 2025).
Era (1 paper, 2025). "The protein expression levels of OPN, sEH, and NOX4, as well as the mRNA expression levels of NOX1 and NOX2, in the Era-induced group were significantly upregulated compared to those in the NC group." (PMID 39754271, 2025). "The protein expression levels of NOX4 and mRNA expression levels of NOX1 and NOX2 in the Era-induced group were significantly upregulated compared to those in the NC group." (PMID 39754271, 2025).
fibro sarcomas (1 paper, 2020). "Nox1 was suggested to be involved in tumor progression, since knockout of this isoform reduced the size of fibro sarcomas, colon, and liver tumors." (PMID 32635630, 2020).
fibromyalgia (1 paper, 2026). A chronic disorder of unknown etiology characterized by pain, stiffness, and tenderness in the muscles of neck, shoulders, back, hips, arms, and legs. "Future translational studies will be essential to validate whether pharmacological modulation of the Schwann cell TRPA1/NOX1 pathway could provide clinical benefit in fibromyalgia." (PMID 41906627, 2026).
fungal infection (1 paper, 2013). "It remains to be determined whether Nox1 has similar protective effects against the lung inflammation and injury evoked by other viruses such as rhinovirus and respiratory syncytial virus (RSV), or by acute or chronic bacterial and fungal infection." (PMID 23577160, 2013).
generalized anxiety disorder (1 paper, 2025). An anxiety disorder characterized by excessive and difficult-to-control worry about a number of life situations. "We investigated the levels of NOX1 and GPER in patients with Generalized Anxiety Disorder." (PMID 40619989, 2025).
hepatoblastoma (1 paper, 2015). Hepatoblastoma (HB) is a malignant hepatic tumor and is the most common pediatric liver cancer. "In human hepatoblastoma cells HepG2, NOX1 knockdown prevents autocrine growth through decreasing EGFR and TGF-α in a p38 MAPK and AKT dependent manner." (PMID 25806803, 2015). "In order to gain insight into the involvement of NOX1 in controlling cellular processes in human hepatoblastoma cells, we used HepG2 cells stably expressing shRNA against NOX1 or a control shRNA." (PMID 25806803, 2015). "Our results reveal a manifold involvement of NOX1 in the metabolic remodeling of hepatoblastoma cells towards a sustained production of building blocks required to maintain a high proliferative rate, thus rendering NOX1 a potential target for cancer therapy." (PMID 25806803, 2015).
hyperplastic polyp (1 paper, 2020). A polyp found mainly in the stomach and colon. "NOX1 protein staining was strongest toward the luminal surface of the cells in colonic tubular adenomas, whereas it was weak to moderate in hyperplastic polyps along the apical and luminal surface of the cells." (PMID 32428030, 2020).
ileitis (1 paper, 2020). "Since pathology in B6 Gpx1/2‐DKO mice shows a dependence on NOX1, we doubt that ER stress generates the ileitis, although when pathology is underway ER stress may contribute to the Paneth cell loss." (PMID 32810389, 2020). "Our hypothesis for linking microbiota to ileitis was based on the idea that Lactobacillus‐induced NOX1 oxidant generation produces damage on its own, which DUOX2 augments." (PMID 32810389, 2020).
infarction (1 paper, 2015). A localised pathological necrosis of tissue resulting from obstruction of the blood supply usually by a thrombus, an embolus, or vascular torsion. "After reperfusion, infarction size, level of superoxide and 8-hydroxy-2′-deoxyguanosine (8-oxo-2dG), and Nox1 immunoreactivity were determined." (PMID 25617620, 2015).
Insulin resistance (1 paper, 2019). Increased resistance towards insulin, that is, diminished effectiveness of insulin in reducing blood glucose levels. "Excess superoxide production derived from NOX1 and NOX2 in response to high glucose or a diabetic setting results in impaired endothelial function and insulin resistance." (PMID 31382355, 2019). "Animal models of T2D indicate that antagonism of NOX1 and NOX2 restores endothelium-dependent vasodilation, while NOX4 has dynamic contributions to insulin resistance." (PMID 31382355, 2019).
ischemia reperfusion injury (1 paper, 2013). Adverse functional, metabolic, or structural changes in ischemic tissues resulting from the restoration of blood flow to the tissue (reperfusion), including swelling; hemorrhage; necrosis; and damage from free radicals. "Overproduction of reactive oxidative species (ROS) by NADPH oxidase is generally considered to play a critical role in the pathogenesis of ischemia reperfusion injury, and there are a number of NADPH homologs, such as Nox1, Nox2 (also named as gp91phox), and Nox3-4." (PMID 24369442, 2013).
kidney failure (1 paper, 2021). An acute or chronic condition that is characterized by the inability of the kidneys to adequately filter the blood. "Regarding the functional significance of Nox subtypes up-regulation, in a previous comprehensive study, it was demonstrated that the induction of Nox4 rather than Nox1 or Nox2 is implicated in ROS overproduction and oxidative stress-induced kidney failure." (PMID 34572988, 2021).
lipodystrophy (1 paper, 2021). A congenital or acquired disorder characterized by abnormal loss or redistribution of the adipose tissue in the body. "On the other hand, Nox1 inhibition with GKT771 markedly reduced Phe-mediated constriction and restored it to baseline levels, suggesting that lipodystrophy increases adrenergic contractility via elevated Nox1 activity." (PMID 34638939, 2021).
lymphoma (1 paper, 2014). A malignant (clonal) proliferation of B- lymphocytes or T- lymphocytes which involves the lymph nodes, bone marrow and/or extranodal sites. "Here, we observed elevated level of ROS as well as expression and activity of ROS producing enzyme NOX1 and NOX2 in liver of DL mice as compared to normal mice, suggesting oxidative microenvironment in liver of lymphoma bearing mice." (PMID 24932681, 2014).
malaria (1 paper, 2025). Malaria is a serious and sometimes fatal disease caused by a parasite that commonly infects a certain type of mosquito which feeds on humans. "Notably, Slc7a11 exhibits unique biological functions in malaria parasite liver‐stage infection regulation: targeted inhibition of GPX4 or SLC7A11 significantly suppresses parasite proliferation through enhanced LPO, whereas NOX1 (NADPH oxidase 1, NADPH1) and TFR1 blockade produces opposing effects." (PMID 40919133, 2025).
mastitis (1 paper, 2024). Inflammation of breast tissue during lactation or postpartum due to an obstructed duct or infection. "Upregulation of NOX1 suggests the priming of the NADPH oxidase complex for potential ROS production in response to minor mastitis-causing bacteria." (PMID 38922009, 2024). "The current study showed that bovine neutrophil exposure to minor mastitis-causing bacteria resulted in the upregulation of genes associated with key components involved in ROS generation, with a specific focus on NOX1, CYBA (p22phox), and SOD1 potentially playing a prominent role in this response." (PMID 38922009, 2024).
Miscarriage (1 paper, 2022). A pregnancy that ends at a stage in which the fetus is incapable of surviving on its own, defined as the spontaneous loss of a fetus before the 22th week of pregnancy. "The present study also showed a strong positive correlation between BPA concentration and tobacco smoking in women with miscarriage, which suggests that BPA increases the risk of pregnancy loss by activating the ROS/NETs pathway due to its concomitant correlation with NOX1 and NCF2." (PMID 36181646, 2022). "Elevated concentrations of NOX1 and NCF2 in “NETs-positive” women with miscarriage seem to indicate the increased activity of NADPH oxidase, a key enzyme involved in the initiation of NET formation." (PMID 36181646, 2022). "As there are no studies focusing on NOX1 and NCF2 in pregnant women or women with miscarriage in the literature, we could not compare the results obtained in this study." (PMID 36181646, 2022).
Multiple Myeloma (1 paper, 2020). "NOX1 is produced by fibroblast and osteoclast cells that play a crucial role in the development and survival of myeloma cells in the bone marrow." (PMID 32856850, 2020).
Myocardial fibrosis (1 paper, 2022). "Silencing of NOX1 was found to attenuate myocardial fibrosis and oxidative stress in HG-induced cardiac fibroblasts." (PMID 36225554, 2022). "The upregulation of NOX1 expression promoted myocardial fibrosis through the activation of the TLR2/NF-κB pathway." (PMID 36225554, 2022). "The inhibition of NOX1 expression alleviated cardiac dysfunction, reduced myocardial fibrosis, and inhibited oxidative stress in DCM." (PMID 36225554, 2022). "In this study, NOX1 was found to aggravate the progression of DCM by promoting myocardial fibrosis and oxidative stress induced by high glucose." (PMID 36225554, 2022). "DCM rats elicited myocardial fibrosis exacerbation, which was accompanied by a marked elevation of NOX1 expression in cardiac tissue." (PMID 36225554, 2022). "In particular, a specific NOX1 inhibitor, ML171, effectively decreased myocardial fibrosis and protected against cardiac dysfunction in DCM rats." (PMID 36225554, 2022). "However, the role of NOX1 in myocardial fibrosis in DCM has never been mentioned." (PMID 36225554, 2022).
myopia (1 paper, 2025). "Herein, we report the differential expression of NGF, BDNF, and related receptors between myopia and high myopia, and their association with NO/nitrites/iNOS/NOX1/4, KEAP1/NRF2, and some epigenetic factors (HDMT3α, HD1), as observed from studies on aqueous and myopic LEC." (PMID 40650128, 2025). "Herein, we observed an increased expression of transcripts specific to iNOS and two metabolic enzymes, NOX-1 and NOX-4, and these targets were particularly increased in high myopia with respect to myopia." (PMID 40650128, 2025). "iNOS, NOX1, and NOX4 transcripts’ expressions are significantly different between myopia and high myopia, implying a differential oxidative stress signature." (PMID 40650128, 2025).
neuropathic pain (1 paper, 2020). Chronic pain caused by damage to nerve fibers. "Their protective effects against neuropathic pain were mediated by inhibiting NOX-1, iNOS, by increasing the enzyme activity of catalase, and inhibition of inflammatory mediators, NF-κB, TNF-α, lipoxygenase, COX-2 enzymes, and PGE2." (PMID 33239680, 2020).
non-alcoholic fatty liver disease (1 paper, 2019). "A recent report also showed upregulation of NOX1 in non-alcoholic fatty liver disease (NAFLD), which impaired the hepatic microcirculation through formation of protein nitrotyrosine adducts and by reducing NO availability." (PMID 31718044, 2019).
ocular hypertension (1 paper, 2021). Abnormally high intraocular pressure. "The mRNA level of NOX2 but not NOX1 is upregulated in retinas with ocular hypertension, and it is thought that NOX2-dependent ROS production is involved in the reduced endothelium-dependent relaxation of retinal blood vessels in the presence of ocular hypertension." (PMID 33557289, 2021).
ovarian carcinoma (1 paper, 2018). A malignant neoplasm originating from the surface ovarian epithelium. "Correspondingly, depletion of NOX1 and NOX4 significantly rescued the growth inhibition of tumors formed by PARP1-depleted ovarian cancer cells." (PMID 29684820, 2018).
ovarian tumors (1 paper, 2011). "In breast and ovarian tumors, crosstalk between mitochondria and NADPH oxidase requires mitochondrial production of ROS and Nox1, and loss of Nox1 signaling contributes to breast and ovarian tumorigenesis." (PMID 21975039, 2011).
overnutrition (1 paper, 2020). An imbalanced nutritional status resulting from excessive intake of nutrients. "In the myocardium, early overnutrition was associated with a significant increase in the gene expression of the proinflammatory markers IL-1β (p < 0.05), IL-6 (p < 0.01), TNF- α (p < 0.05), and LO (p < 0.05), and the pro-oxidant enzymes NOX-1 (p < 0.05) and NOX-4 (p < 0.01)." (PMID 32093229, 2020).
polycystic ovary syndrome (1 paper, 2022). A disorder that manifests as multiple cysts on the ovaries. "The suppressive action of TfR/NADPH oxidase 1/PTEN, which induced kinase 1 acyl-CoA synthetase long chain family member 4 signaling on folliculogenesis, is a likely target for polycystic ovary syndrome." (PMID 36293552, 2022).
prediabetes (1 paper, 2022). "The concentration of AKR1B1, NOX1, MDA, SOD and GPx was measured between the NDP and PD group at the end of the prediabetes induction period." (PMID 35918636, 2022).
presbycusis (1 paper, 2020). Bilateral hearing loss caused by progressive degeneration of cochlear structures and central auditory pathways, typically associated with the aging process. "As the absence of p22phox abolishes NOX1–4 catalytic activity, our data strongly support a role of NOX-derived ROS in presbycusis." (PMID 32000019, 2020).
small intestinal adenocarcinomas (1 paper, 2020). "A representative section from a small intestinal adenocarcinoma demonstrated moderately strong cytoplasmic NOX1 immunostaining with a more concentrated expression in the luminal surface of the glands." (PMID 32428030, 2020).